EGFR (epidermal growth factor receptor)
Diseases named in the same sentence as EGFR in open-access papers (continued):
Sharing a sentence is not in itself a finding about the gene and the disease.
cancer (continued). "Considering the constitutive activation of EGFR signalling in cancer drives cell proliferation, resistance to chemotherapy, and metastasis, HDAC6 responses may also contribute to EGFR responses in cancer." (PMID 39941046, 2025). "Several derivatives of pyrido[2,3-d]pyrimidine have shown promising EGFR inhibitory effects II–IV, as well as activity against resistant mutations VI–VII, making them good candidates for developing next-generation inhibitors effective against mutant EGFR in cancer drug development." (PMID 41155588, 2025). "Transforming growth factor-alpha has long been recognized as a factor that may contribute to cancer development, particularly due to its role in EGFR activation." (PMID 40410803, 2025). "Notably, silencing CXCR7 not only reverses the resistance of epidermal growth factor receptor (EGFR)-mutant NSCLC cells to EGFR tyrosine kinase inhibitors (TKIs) but also promotes the transition of cancer cells to an epithelial phenotype." (PMID 40136462, 2025). "CAPN2 promoted cancer progression and chemotherapy resistance through the EGFR/AKT pathway." (PMID 41423496, 2025). "Furthermore, EGFR’s interaction with mitochondrial proteins such as Mfn1 disrupts mitochondrial fusion, further supporting its role in cancer progression." (PMID 41145430, 2025). "Finally, we highlight emerging technologies such as artificial intelligence, mutation-specific peptides, and multimodal imaging platforms, which offer significant potential for advancing the diagnosis and treatment of EGFR-targeted cancers." (PMID 40906195, 2025). "Exploring the mechanisms through which FUT1 influences drug sensitivity could lead to more personalized and effective treatment strategies, especially for patients with EGFR-mutant cancers." (PMID 40084262, 2025). "Previous studies have reported that CD44 interacts with TGFβR1 30 or EGFR 29 in cancer." (PMID 40860188, 2025). "Notably, plant-derived compounds such as curcumin, resveratrol, and EGCG have been shown to inhibit EGFR signaling and its downstream pathways, exerting anti-proliferative and anti-inflammatory effects in cancer models." (PMID 40508016, 2025). "Consequently, EGFR is considered a promising therapeutic target in cancer treatment, particularly for NSCLC." (PMID 40076971, 2025). "Further off-target resistance may be driven by aberrant downstream EGFR signalling affecting various common cancer-related pathways." (PMID 40002158, 2025). "Indeed, DeepDR forecasted the IC50 values of 265 drugs and the drug responses of 33 cancer types (e.g. EGFR inhibitors in non-small lung cancer and." (PMID 41402855, 2025). "By screening for other compounds that might be effective in inhibiting the emergence of cells with different mechanisms of resistance to EGFR-TKIs, we identified sorafenib and showed it to be specific for EGFR addicted cancer cells." (PMID 40846697, 2025). "CircEGFR is derived from the EGFR gene which is a well‐established oncogene in various cancers." (PMID 40008750, 2025). "The EGF/EGFR signaling pathway may play a role in regulating FAS-mediated apoptosis in cancer cells." (PMID 41188939, 2025).
cancer (continued). "However, several potential pathways have been identified in other cancers, including the epidermal growth factor receptor (EGFR)/ERK signaling pathway, the Janus kinase (JAK)/STAT signaling pathway, and the ERK/mitogen-activated protein kinase (MAPK) pathway." (PMID 40141328, 2025). "These days, a sizable fraction of human cancer cells overexpress EGFR." (PMID 40745188, 2025). "In contrast with YAPoff cancers, YAPon cancers exhibit higher sensitivity to various kinase inhibitors, particularly those in the EGFR/MEK/ERK pathway, as well as genetic vulnerabilities to various genes involved in integrin and extracellular matrix signaling and cytoskeletal organization." (PMID 40440076, 2025). "Epidermal growth factor receptor is a protein involved in cancer cell proliferation, differentiation, and invasion, and regulation of splicing and suppression of function by AS-oligo could be a strategy for treating cancer." (PMID 40076889, 2025). "In the current study, we provided critical evidence about the association between USP11 and EGFR or TLR signals in CRC; first, the high expression of USP11 in CRC tissues and its association with cancer-related gene sets suggest that USP11 plays an essential role in CRC development." (PMID 41419456, 2025). "Since it is well documented that cancer cell-derived EVs deliver EGFR to other cells, we sought to determine whether ADSCs-EVs could also contain and deliver EGFR to OC cells." (PMID 39759123, 2025). "Pathologically, EGFR’s role in the development of human cancers through its dysregulation, including its overexpression, overproduction of its ligands, and altered triggering of its tyrosine kinase domain (TKD) activity by point mutation, has been well studied." (PMID 38888847, 2025). "We tested TF expression, along with EGFR expressions, in cancer tissue specimens." (PMID 39751657, 2025). "Subsequent studies using EGFR and BRAF inhibition with vemurafenib and cetuximab in Class 1 BRAF-mutant CRC revealed mild improvements in ORR, but still did achieve the clinical efficacy of single-agent BRAF inhibition in other BRAF-mutated cancer types." (PMID 41294686, 2025). "However, due to limited reports, the precise impact of EGFR expression in immune cells on cancer cell development remains to be comprehensively explored." (PMID 40859900, 2025). "Therefore, HER2 and c-MET are targets for cancer treatments, including targeted therapies and drugs that can also block other proteins, such as EGFR." (PMID 40430804, 2025). "Therefore, while the study highlights the synergistic potential of the combination and its mechanism, the results concerning Erlotinib’s individual activity should be addressed cautiously when considering EGFR-driven cancers." (PMID 40243485, 2025). "The EGFR/STAT signaling pathway plays a critical role in cancer pathogenesis." (PMID 41312415, 2025). "This study paves the way for NIR-based endoscopic imaging in EGFR-overexpressing cancer diagnosis." (PMID 40906195, 2025). "In addition, PM2.5 exposure induces aryl hydrocarbon receptor (AhR)-dependent transcription of transmembrane serine protease 2 (TMPRSS2) and interleukin-18 (IL-18), further promoting cancer progression in EGFR-mutant cells." (PMID 39578555, 2025). "EGFR is overexpressed in many types of cancer, including HNSCC." (PMID 40864738, 2025). "Given that EGFR inhibitors are already approved for cancer therapy, EGFR could represent a promising candidate for repurposing as a therapeutic target for LOAD." (PMID 41427057, 2025). "However, signal blockade by these HER2 and EGFR inhibitors induces compensatory responses in cancer cells, such as the overexpression and dimerization of other RTKs (e.g., HER3, MET), activating bypass pathways and ultimately leading to therapeutic resistance." (PMID 40872476, 2025).
cancer (continued). "EGFR-TKIs from different generations, including gefitinib, afatinib, and osimertinib, have been approved for cancer treatment, leading to improved objective response rates and extended progression-free survival in patients, demonstrating positive therapeutic outcomes." (PMID 40172117, 2025). "In the current study, the fluorescence of synthesized Pan‐IR700 was found on the cell surface membrane, indicating that Pan‐IR700 can bind specifically to the EGFR protein on the plasma membrane of cancer cells, consistent with the findings in previous studies using Pan‐IR700 in other cell lines." (PMID 40830817, 2025). "In vitro studies show that these nanosheets could be internalized selectively into EGFR‐positive cancer cells and effectively eliminate these cells mainly through photothermal‐induced apoptosis." (PMID 39717005, 2025). "The epidermal growth factor receptor (EGFR) plays a crucial role in the development of cancer." (PMID 41155569, 2025). "Biochemical mechanisms involving EGFR may promote the development of cancer tissue in the event of such an abnormality." (PMID 39561105, 2025). "Some cancer patients have resistance to these drugs due to alterations in EGFR." (PMID 40332084, 2025). "Alternatively, exogenous loading can also be achieved by covalently attaching the cargo proteins to the EV, such as conjugating an anti-EGFR peptide to facilitate the accumulation of EVs in EGFR-positive cancer cells, although this approach also has its limitations." (PMID 39860010, 2025). "The second receptor we selected for active delivery of B4C nanoparticles to cancer cells is EGFR." (PMID 40438187, 2025). "Moreover, cancer cells that survive the blockade of ERK1/2 combined with EGFR TKI treatment enter a senescence-like phenotype characterized by high YAP/TEAD activity." (PMID 40597785, 2025). "The activation of EGFR signaling is critical for cancer progression and chemoresistance in CRC." (PMID 39560161, 2025). "Indeed, doxorubicin alone,and in combination with SLURP-1, suppresses the expression of this receptor intumors.EGFR mediates the growth, migration andsurvival of cancer cells." (PMID 40264586, 2025). "Clearly, mutant EGFR is an important target of cancer therapeutics." (PMID 40940888, 2025). "We found that MET and/or fibroblast growth factor receptor (FGFR) activation by CAFs could repeatedly rescue EGFR-mutant cancers." (PMID 40002883, 2025). "Targeting EGF can inhibit the growth of cancer cells overexpressing EGFR." (PMID 40859900, 2025). "Finally, we also discuss the opportunities and future prospects regarding the combined use of Lingzhi/Yunzhi and EGFR-TKIs in cancer patients." (PMID 40733125, 2025). "While the role of EGFR in the mitochondrial compartment remains unclear, the treatment of PC3 cancer cells with AEE788 (an EGFR inhibitor) causes mitochondrial fission while EGF-mediated activation of EGFR leads to fusion of the mitochondria." (PMID 40004137, 2025). "Thus, our studies uncover ESSENCE as an important cancer biomarker upregulated by the EGFR/MAPK/EGR1 pathway and also provide insight into CRC diagnosis and treatment." (PMID 40190348, 2025). "Therefore, 34 pan-cancer scRNA-Seq datasets were included to screen important EGFR-related genes for EGFR.Sig." (PMID 40574864, 2025). "We examined the correlation between WBP5 and EGFR expressions in various cancer types." (PMID 40002180, 2025). "The EGFR autocrine pathway plays a crucial role in human cancer since it contributes to a number of highly relevant processes in tumor development and progression, including cell proliferation, regulation of apoptotic cell death, angiogenesis, and metastatic spread." (PMID 39859343, 2025). "A computational method capable of accurately predicting capacitance values based solely on initial morphological features would significantly improve the reliability of EGFR-based cancer diagnostics by eliminating the confounding effects of time-dependent morphological changes." (PMID 41294763, 2025).
cancer (continued). "This makes it possible to screen cancers feasible for receiving CAP treatment and enables the design of innovative therapeutics via stimulating EGFR(Y1068) phosphorylation instead of blocking the whole EGFR receptor for treating cancers with little adverse effect." (PMID 39781456, 2025). "It has been shown that DHA/EPA-enriched membranes can disrupt the lipid raft structure in cancer cell membranes, leading to the depolymerization of the epidermal growth factor receptor (EGFR) from the lipid rafts and impairing the activity of its downstream signaling pathways." (PMID 40808836, 2025). "However, uncontrolled EGFR activation can be detrimental, leading to fibrosis, inflammation, and even cancer development." (PMID 39966897, 2025). "EGFR-TKI resistance is one of the biggest issues in cancer treatment, especially in NSCLC." (PMID 40728967, 2025). "The degree of the radiation-induced stemness response of cancer cells mediated by the EGFR-Hippo signaling pathway might be a potential predictor of the efficacy of radiotherapy and the development of radioresistance." (PMID 40003899, 2025). "While EGFR signaling is a central target in metastatic CRC therapy, ANXA1 may enhance both EGFR activation and stabilization, thereby contributing to cancer immune evasion via the ANXA1/EGFR interaction." (PMID 41283264, 2025). "Thus, nuclear EGFR (nEGFR) accumulation is a potential therapeutic target that rarely occurs outside the context of cancer, and full-length EGFR seems to translocate to the nucleus." (PMID 39940647, 2025). "Guided by these results, we developed a highly multiplexed parallel reaction monitoring (PRM) assay for precise quantitation of 90 proteins that are associated with cancer metabolism, RNA regulation, and major cancer growth–associated pathways, such as PI3K/AKT/mTOR and EGFR/RAS/RAF." (PMID 39723668, 2025). "The high expression of genes like EGFR may have a pro-cancer effect and serve as potential biomarkers for ccRCC molecular subtyping and targeted therapy, but larger-scale clinical validation is still needed." (PMID 40104395, 2025). "EGFR is one of the RTKs that is over-activated and promotes cancer progression." (PMID 39948411, 2025). "In addition, radiation-induced stemness-responsive cancer cells should be included in the effect evaluation system of EGFR-targeted therapy combined with radiotherapy." (PMID 40003899, 2025). "Notably, all four KRAS missense mutations have reported resistance to EGFR inhibitors (cetuximab, panitumumab) and HER2 inhibitors (tucatinib + trastuzumab) for various cancers." (PMID 41009531, 2025). "Similarly, luteolin and polyphyllin I synergize with EGFR-TKIs to inhibit cancer cell proliferation and metastasis." (PMID 40535810, 2025). "The presence of EGF allowed the nanoparticles to interact strongly with cancer cells that expressed EGFR, as the cancer cells could take up the cells via EGF receptor-mediated endocytosis." (PMID 40650240, 2025). "EGFR is negatively correlated with gga-miR-16c-5p, gga-miR-155, gga-miR-20b-5p, miR-155-x, and miR-2995-x and is a key regulator of cell proliferation, growth, differentiation, and cancer development." (PMID 39874788, 2025). "Therefore, new strategies and EGFR-targeting anti-cancer drugs are urgently needed for effective cancer treatment with low side effects." (PMID 41140511, 2025). "Searching the top 200 MEGs against the Cancer Gene Census yielded two other hits: EGFR and QKI." (PMID 41048341, 2025). "However, recent studies have elucidated kinase-independent roles of EGFR in cell survival and cancer progression." (PMID 40259053, 2025). "In addition to Fc-mediated immune cell activation, EGFR mAbs are also applied to block the EGFR signaling pathway in cancer." (PMID 40358156, 2025).
cancer (continued). "MRP1, MRP3, MRP4, and MRP5, for instance, have often been found to be overexpressed in gastric adenocarcinoma (GAC), a highly chemoresistant cancer driven by oncogene activation, particularly through the upregulation of efflux pumps via the EGFR, Ras, or MYC pathways." (PMID 40149342, 2025). "A contemporary approach for tackling cancer proliferation involves the inhibition of a trans-membrane glycoprotein, identified as epidermal growth factor receptor (EGFR), which contributes a crucial role in intracellular signaling, morphogenesis, and differentiation." (PMID 40329373, 2025). "Previously, similar rates of VTE were reported with EGFR compared to wildtype cancers." (PMID 39858040, 2025). "EGFR inhibition prevents cancer stem cell clustering and lung metastasis in TNBC." (PMID 41325388, 2025). "The probe could specifically bind to cancer cells expressing EGFR or HER2, thus achieving higher accuracy and specificity." (PMID 40906195, 2025). "Studies have shown that cancer cells treated with epidermal growth factor receptor inhibitors often exhibit increased sensitivity to anticancer drugs, further underscoring the pivotal role of FGF/FGFR signaling in cancer stem cell regulation and highlighting its potential as a therapeutic target." (PMID 40003950, 2025). "The pattern emerging from the first attempts to block EGFR in CRC revealed that this cancer type is addicted to EGFR‐RAS‐MAPK signaling and any perturbation to it will be likely circumvented by molecular events that are able to restore the activity of this signaling axis." (PMID 39470386, 2025). "In addition, it is known that cancer cells alter ganglioside composition to favour receptor dimerisation and signalling as demonstrated for Her2 (ErbB2) and EGFR." (PMID 40941028, 2025). "Additionally, in EGFR-TKI resistant cancer cells, upregulation of miR-21 reduces expression of CCL5, CXCL10, IL-6, IL-8, and TNF-α." (PMID 40058234, 2025). "To evaluate whether the AbEn retained its target-binding capability, we conducted a flow cytometry-based cell binding assay using the EGFR-expressing cancer cell line HCC827." (PMID 41228205, 2025). "Consequently, assessing EGFR expression levels, particularly in cases of overexpression, has gained increasing attention as a valuable tool for cancer screening and treatment management." (PMID 40368641, 2025). "However, dysregulation of EGFR signaling can result in uncontrolled cellular growth and cancer progression." (PMID 40656954, 2025). "The downregulation of VEGFR2 and EGFR expression suggests that 4-TCPA may effectively interfere with key signaling pathways involved in cancer progression." (PMID 40592982, 2025). "Additionally, while four cancer-related proteins were screened, EGFR was chosen for detailed simulation because of its pivotal role in the progression of multiple cancer types." (PMID 41455835, 2025). "The activation of EGFR promotes cellular proliferation and differentiation, and it plays crucial roles in embryonic development, maintenance and repair of adult tissues, and proliferation and metastasis of cancer cells." (PMID 39813112, 2025). "Therefore, EGFR is considered as a key target in combating such uncontrolled proliferation in cancer therapy." (PMID 40344575, 2025). "C. albicans stimulation of EGFR and c-Met likely enhances cancer progression." (PMID 39939579, 2025). "In contrast, KRAS and growth factor receptor mutations like FGFR and EGFR are generally mutually exclusive in cancer, resulting in a lack of sensitivity to the latter in the KRAS hotspot population." (PMID 41168869, 2025). "EGFR is widely recognized in cancer as a cell surface protein that induces cell proliferation." (PMID 39796763, 2025).